ICE2 (interactor of little elongation complex ELL subunit 2)
Description:
Component of the little elongation complex (LEC), a complex required to regulate small nuclear RNA (snRNA) gene transcription by RNA polymerase II and III.
Synonyms: BRCC1; NARG2; FLJ11896
Tractability: PROTAC: ubiquitination databases record sites on it.
Gene: Protein-coding gene on chromosome 15 (60,419,608 to 60,479,160, reverse strand). Ensembl gene ENSG00000128915.
Subcellular location: Nucleus
Subcellular location (Human Protein Atlas): Nuclear bodies; Nucleoplasm; Cytosol
Pathways (Reactome):
Gene expression (Transcription): RNA polymerase II transcribes snRNA genes
Gene Ontology:
Molecular function: protein binding
Biological process: positive regulation of transcription by RNA polymerase III; snRNA transcription by RNA polymerase II; snRNA transcription by RNA polymerase III; positive regulation of snRNA transcription by RNA polymerase II
Cellular component: Cajal body; euchromatin; histone locus body; nuclear body; nucleoplasm; transcription elongation factor complex; nucleus
Genetic constraint (gnomAD): Loss-of-function variants: 52 observed, 65.78 expected, observed/expected ratio (o/e) 0.79, 90% interval 0.63 to 1. The upper end of that interval is the gene's LOEUF score, 1, which puts it in group 4 of 6, group 1 being the genes least tolerant of losing a copy. Missense variants: 995 observed, 901.92 expected, observed/expected ratio (o/e) 1.1, 90% interval 1.05 to 1.16. Synonymous variants: 297 observed, 314.36 expected, observed/expected ratio (o/e) 0.94, 90% interval 0.86 to 1.04.
Homologues: Orthologues: chimpanzee ICE2 (99% identical), macaque ICE2 (98% identical), dog ICE2 (89% identical), pig ICE2 (88% identical), rabbit ICE2 (85% identical), rat Ice2 (77% identical), mouse Ice2 (76% identical), guinea pig ICE2 (75% identical), tropical clawed frog ice2 (37% identical), zebrafish ice2 (27% identical).
Diseases named in the same sentence as ICE2 in open-access papers:
ICE2 is named in the same sentence as 7 diseases in open-access papers, as found by Europe PMC text mining. Sharing a sentence is not in itself a finding about the gene and the disease. The quoted sentences say what the papers report.
breast carcinoma (2 papers, 2015 to 2019). "Interestingly, it predicted positive association in breast cancer through co-relation with MYL6, RABAC1 and other genes, while negatively regulating ATL2, ICE2 and TADA1 in melanoma and HCC." (PMID 30857225, 2019).
fatty liver disease (1 paper, 2024). A reversible condition wherein large vacuoles of triglyceride fat accumulate in liver cells via the process of steatosis. "Other previously unreported variants associated with lipid traits and fatty liver disease, including rs2792735 in GPAM, rs2980888 in TRIB1, rs13389219 in COBLL1, rs8178824 in APOH and rs339969 in ICE2." (PMID 38632349, 2024).
cancer (2 papers, 2015 to 2025). A tumor composed of atypical neoplastic, often pleomorphic cells that invade other tissues. "We found telomere maintaining genes (TERF2, CTC1, and ACD), genes involved in zinc homeostasis (MTF1 and SLC30A9), transcription elongation factor complex components (ICE1, ICE2, ELL), and BCL6 corepressors (BCOR, BCORL1) uniquely invoked in TNBC cancers." (PMID 40700427, 2025).
ICE2 also shares sentences with these, for which no sentence is quoted: asthma (1 paper); leukemia (1); melanoma (1); pancreatic cancer (1).